BLTP1 (bridge-like lipid transfer protein family member 1)
Description:
Bridge-like lipid transfer protein that functions as molecular bridges between endoplasmic reticulum and the membranes targeted for lipid delivery. Forms a tunnel with multiple beta-grooves that allows the transport of phospholipids (By similarity). Provides phosphatidylethanolamine for glycosylphosphatidylinositol (GPI) anchor synthesis in the endoplasmic reticulum. Plays a role in endosomal trafficking and endosome recycling. Also involved in the actin cytoskeleton and cilia structural dynamics. Acts as a regulator of phagocytosis. Required for the formation of endoplasmic reticulum-plasma membrane junctions which are critical for lipid exchange.
Synonyms: FSA; KIAA1109; KIAA1371; TWEEK; FLJ21404; ALKKUCS
Tractability: Antibody: UniProt places it where antibodies can reach, with medium confidence; UniProt predicts a signal peptide or a membrane-spanning region; its Gene Ontology location is reachable by antibodies, with medium confidence. PROTAC: ubiquitination databases record sites on it.
Gene: Protein-coding gene on chromosome 4 (122,152,331 to 122,364,167, forward strand). Ensembl gene ENSG00000138688.
Subcellular location: Endoplasmic reticulum membrane; Apical cell membrane; Cell membrane; Mitochondrion membrane
Subcellular location (Human Protein Atlas): Centrosome; Nucleoplasm
Gene Ontology:
Molecular function: protein binding; phosphatidylethanolamine transfer activity
Biological process: endocytic recycling; endosomal transport; phagocytosis; intermembrane lipid transfer; regulation of cell growth; regulation of epithelial cell differentiation; synaptic vesicle endocytosis; phospholipid transport
Cellular component: endoplasmic reticulum-plasma membrane contact site; membrane; mitochondrial membrane; nucleus; plasma membrane; apical plasma membrane; endoplasmic reticulum membrane; presynapse
Genetic constraint (gnomAD): Loss-of-function variants: 213 observed, 411.81 expected, observed/expected ratio (o/e) 0.52, 90% interval 0.46 to 0.58. The upper end of that interval is the gene's LOEUF score, 0.58, which puts it in group 2 of 6, group 1 being the genes least tolerant of losing a copy. Missense variants: 3,725 observed, 5,250.6 expected, observed/expected ratio (o/e) 0.71, 90% interval 0.69 to 0.73. Synonymous variants: 1,605 observed, 1,788.7 expected, observed/expected ratio (o/e) 0.9, 90% interval 0.86 to 0.94.
Gene-disease validity (ClinGen):
ClinGen rates the evidence that BLTP1 causes each of these diseases.
Alkuraya-Kucinskas syndrome (autosomal recessive): Definitive.
Homologues: Orthologues: macaque BLTP1 (98% identical), chimpanzee BLTP1 (98% identical), pig BLTP1 (98% identical), dog BLTP1 (96% identical), rabbit BLTP1 (96% identical), rat Bltp1 (95% identical), mouse Bltp1 (95% identical), guinea pig BLTP1 (88% identical), tropical clawed frog bltp1 (85% identical), zebrafish kiaa1109 (73% identical), Drosophila melanogaster tweek (33% identical), Caenorhabditis elegans lpd-3 (19% identical).
Diseases named in the same sentence as BLTP1 in open-access papers:
BLTP1 is named in the same sentence as 46 diseases in open-access papers, as found by Europe PMC text mining. Sharing a sentence is not in itself a finding about the gene and the disease. The quoted sentences say what the papers report.
Alkuraya-Kučinskas syndrome (6 papers, 2018 to 2026). "Variants of the more recently characterized BLTP1 underlie Alkuraya-Kučinskas syndrome, a severe neurodevelopmental disorder also discussed here." (PMID 41522673, 2026). "As mutations in BLTP1, the human orthologue of lpd-3, cause Alkuraya-Kucinskas syndrome, LPD-3 family proteins may serve as evolutionarily conserved highway bridges critical for ER-associated non-vesicular lipid trafficking and resilience to cold stress in eukaryotic cells." (PMID 36357390, 2022). "Mutations in the human orthologue KIAA1109/BLTP1 cause Alkuraya-Kucinskas syndrome, a neuro- and cardiovascular development disorder with no known medical treatment." (PMID 36357390, 2022).
Obesity (2 papers, 2022 to 2025). Accumulation of substantial excess body fat. "Potentially conserved roles of KIAA1109/BLTP1 and other mammalian homologues of LPD-3 in regulating lipid trafficking and lipogenesis also raise the possibility of targeting KIAA1109/BLTP1 in diverse lipid metabolic disorders, including fatty liver diseases and obesity." (PMID 36357390, 2022).
BLTP1 also shares sentences with these, for which no sentence is quoted: asthma (6 papers); celiac disease (6); cancer (5); rheumatoid arthritis (4); type 1 diabetes (4); autoimmune disease (3); developmental delay (3); juvenile idiopathic arthritis (3); allergic rhinitis (2); arthrogryposis (2); Autoimmunity (2); Hydrocephalus (2); Intellectual disability (2); Pleural effusion (2); prostate carcinoma (2); systemic lupus erythematosus (2); ulcerative colitis (2); Allergy (1); amyotrophic lateral sclerosis (1); anterior uveitis (1); Behçet’s disease (1); cervical tumors (1); Dandy-Walker malformation (1); early-onset epilepsy (1); eczema (1); endometrial cancer (1); eosinophilia (1); esophageal squamous cell carcinoma (1); fatty liver disease (1); Graves disease (1).
A further 14 diseases each share a sentence with BLTP1 in 1 paper.